INS (insulin)
Diseases named in the same sentence as INS in open-access papers (continued):
Sharing a sentence is not in itself a finding about the gene and the disease.
type 2 diabetes (continued). "Currently, effective therapeutic options exist to restore responsiveness to insulin in type 2 diabetes; however, insulin therapy is not only necessary for type 1 diabetes, but also for type 2 diabetes." (PMID 23829275, 2013). "On the other hand, incretin-based therapy has several potential sites of action for the treatment of type 2 diabetes ranging from increasing insulin secretion, reducing glucagon secretion, and regulating glucose control." (PMID 24069048, 2013). "It is notable that some pharmacological treatment delaying the onset of type 2 diabetes is also able to improve insulin clearance in IGT individuals." (PMID 24194886, 2013). "The present study confirms the findings of recently published trials, in both Type 1 diabetes 17 and Type 2 diabetes basal–bolus therapy 16, which demonstrated an improvement in health-related quality of life with insulin degludec vs. insulin glargine." (PMID 23199058, 2013). "In view of the many restrictions on the use of oral antidiabetic drugs, temporary insulin treatment remains the most practical means of glycemic control for many hospitalized patients with type 2 diabetes." (PMID 23574917, 2013). "With the progressive development of type 2 diabetes, patients eventually require insulin in order to bring their condition under control." (PMID 24223662, 2013). "Pio has also been shown to preserve insulin secretion and pancreatic morphology in three models of type 2 diabetes." (PMID 23762423, 2013). "In contrast to the loss of insulin-producing pancreatic beta cells characteristic of type 1 diabetes, type 2 diabetes results from a progressive insulin secretory defect overlaid on a background of insulin resistance." (PMID 23547788, 2013). "Ten Japanese insulin-treated type 2 diabetic patients aged 34–83 years old and on HD were recruited for this study." (PMID 23445717, 2013). "M2 macrophages are known to maintain glucose tolerance, insulin sensitivity and general adipocyte function that can prevent development of obesity due to diet and type-2 diabetes." (PMID 23383064, 2013). "The subjects were representative for patients with Type 2 diabetes starting on basal insulin therapy, with disease duration of 9.5 years, HbA1c above target [67 mmol/mol (8.3%)] and moderate obesity (BMI 25–33 kg/m2)." (PMID 23199058, 2013). "The 24 h excretion rate of 8-iso PGF2α was much higher (P < 0.001) in type 2 diabetic patients treated with oral hypoglycaemic agents alone than in type 2 diabetes group treated with insulin." (PMID 23577222, 2013). "Type 2 diabetes is characterized by excessive blood glucose and insulin resistance due to an improper insulin response of the body to manage glucose from the diet." (PMID 24069048, 2013). "Assessment of insulin secretion is potentially helpful in clinical practice: differences in glycaemic treatment requirements between Type 1 and Type 2 diabetes mainly relate to the development of absolute insulin deficiency in the former." (PMID 23413806, 2013). "GLP-1 has been administered as a continuous infusion in type 2 diabetics with impressive insulin-sensitizing effects, reduced insulin resistance in skeletal muscle and adipose tissue, and improvements in insulin-mediated glucose uptake." (PMID 23777457, 2013). "This trial also found reductions in fasting glucose and fasting insulin, and resulted in a 54% and 76% (depending on the dose) reduction in the annualized incidence rate for the progression to type 2 diabetes among all patients studied." (PMID 23514437, 2013). "Specifically, skeletal muscle is the largest contributor to whole-body glucose disposal, making defective insulin signaling in skeletal muscle a primary feature of type 2 diabetes." (PMID 23437325, 2013). "Insulin treatment can lead to good glycemic control and result in improvement of lipid parameters in type 2 diabetic patients." (PMID 23617853, 2013). "The decreased insulin secretion capacity plays a definite role in the development of type 2 diabetes." (PMID 23876034, 2013).
type 2 diabetes (continued). "Type 2 diabetes mellitus (T2DM) is characterized by chronic hyperglycemia as a result of defects in insulin sensitivity." (PMID 24386644, 2013). "Excessive secretion of glucagon, a functional insulin antagonist, significantly contributes to hyperglycemia in type 1 and type 2 diabetes." (PMID 23744070, 2013). "The extract from persimmon peel modified expression of insulin signaling pathway-related genes and increased insulin receptor beta tyrosine phosphorylation, improving insulin resistance in the liver of type 2 diabetic Goto-Kakizaki rats." (PMID 24967258, 2013). "Molecular and cellular studies in animal models have demonstrated that zinc (Zn) plays a key role in the synthesis and action of insulin under normal physiological conditions, and that zinc supplementation can be protective in rodent models of type 2 diabetes." (PMID 23613929, 2013). "The region also contains several genes associted with obesity or metabolic syndrome such as ENPP1 with obesity and risk of glucose intolerance and type 2 diabetes, SGK1 with insulin secretion in type 2 diabeties." (PMID 23977060, 2013). "Elevated levels of plasma free fatty acids have been shown to reduce insulin-stimulated glucose uptake in both young healthy subjects, and, in those with type II diabetes." (PMID 24391874, 2013). "Co-treatment of cholesterol-loaded macrophages with HDL would ameliorate the effects of acLDL on insulin-stimulated skeletal muscle glucose uptake in myotube cultures from patients with type 2 diabetes." (PMID 23437184, 2013). "Destruction of the pancreatic beta cells results in decreased insulin production and manifests as type II diabetes, a condition that is characterized by excess extracellular glucose with an intracellular deficit." (PMID 23607096, 2013). "Impaired insulin action plays a major role in the pathogenesis of type 2 diabetes, a chronic metabolic disorder which imposes a tremendous burden to morbidity and mortality worldwide." (PMID 23894607, 2013). "They enhance insulin action, improve glycemic control, reduce the level of glycohemoglobin (HbA1C), and have variable effects on serum triglyceride levels in type 2 diabetic patients." (PMID 25374688, 2013). "A retrospective multicentre parallel two-arm study included 301 patients with type 2 diabetes already on treatment with biphasic human insulin twice daily (bd) in combination with OAD." (PMID 23916120, 2013). "In this study, we examined the efficacy of incretin therapy in patients with insulin-treated type 2 diabetes undergoing hemodialysis." (PMID 23445717, 2013). "Fibrillation of insulin poses a problem in its long-term storage, reducing its efficacy in treating type II diabetes." (PMID 24009675, 2013). "PPARγ agonists including Rosi and piglitazone are potent agents in treatment of type-2 diabetes mainly via sensitizing the insulin signaling." (PMID 24489534, 2013). "In effect, about 20% of patients with type 2 diabetes in the western world are lean and relatively insulin sensitive, a condition that has become widespread in the developing world." (PMID 23408938, 2013). "In an observational study, 60 patients with type 2 diabetes were treated by oral hypoglycaemic agents alone, and 31 patients with type 2 diabetes were treated with insulin plus oral hypoglycaemic agents." (PMID 23577222, 2013). "The patient population comprised insulin-naïve subjects with type 2 diabetes currently treated with 1–2 OADs qualifying for intensified treatment." (PMID 23577643, 2013). "Type 2 diabetes is characterized by decreased insulin sensitivity in major target organs such as liver, muscle, and adipose tissues, in addition to a decreased insulin secretion by the beta pancreatic cells." (PMID 23864882, 2013). "In this study, IUGR neonatal lambs had enhanced in vitro glucose-stimulated insulin secretion, or β-cell hypersecretion relative to control lambs, which occurs in obese individuals, as well as early in the pathogenesis of type 2 diabetes." (PMID 23424667, 2013).
type 2 diabetes (continued). "In this meta-analysis, we had analysis the effect of AGIs on glucose, insulin secretion and weight against placebo or other active oral hypoglycemic agents in Asian and Caucasian type 2 diabetes patients." (PMID 24236131, 2013). "It is well established that obesity generates a state of chronic, low-grade inflammation in liver and adipose tissue, accompanied by the secretion of signaling proteins that prevent fat cells from responding to insulin, which leads to type 2 diabetes." (PMID 24368730, 2013). "After exercise, insulin sensitivity (M values) increased by 11% (P < 0.05) in lean, 15% (P < 0.05) in obese, and 32% (P < 0.05) in type 2 diabetes groups." (PMID 23671849, 2013). "Our study in the S2814D mouse model elucidates the gain-of-function defect in RyR2 due to CaMKII hyperphosphorylation as a novel mechanism that alters insulin secretion due to β cell dysfunction, thereby contributing to the development of type 2 diabetes." (PMID 23516528, 2013). "As fetuses of a more highly insulin-resistant condition are more likely to develop metabolic syndromes and type II diabetes, this finding would be help to understand the mechanism in development and prevention of mother-baby diabetic cycle." (PMID 23560057, 2013). "High caloric intake increases the risk of type 2 diabetes mellitus (T2DM) by increasing body weight, thus decreasing insulin sensitivity." (PMID 24077241, 2013). "Although metformin can lower blood glucose, the levels rarely remain within the normal range and as the type 2 diabetes progresses, additional medication such as exogenous insulin is often required to control patients’ hyperglycaemia." (PMID 23663483, 2013). "Patients with type 2 diabetes have a complex phenotype with impaired insulin secretion, insulin resistance both in the liver and peripheral tissues, and increased hepatic glucose production, all of which contribute to the development of overt hyperglycemia." (PMID 23671880, 2013). "Another study demonstrated a 28% improvement in insulin sensitivity after treatment with 30 mg pioglitazone for 26 weeks; but as their participants had type 2 diabetes, they are also likely to have shown an exaggerated response compared to our study group." (PMID 23516412, 2013). "Our observation that resveratrol was able to induce insulin synthesis in α-cells is germane since it currently is undergoing clinical trials for treatment of type 2 diabetes." (PMID 24330680, 2013). "Type 2 diabetes is characterized by impaired insulin secretion and reduced peripheral insulin sensitivity." (PMID 23298687, 2013). "There is evidence that insulin-resistant obese individuals with type 2 diabetes have approximately 30% fewer mitochondria in their skeletal muscle than age-matched healthy controls." (PMID 23815800, 2013). "For example, weight gain and hypoglycemia have been reported as significant reasons for discontinuation/switching of insulin therapy among patients with type 2 diabetes." (PMID 23799930, 2013). "The vanadate derivatives bis(ethylmaltolato)oxovanadium(IV) and bis(maltolato)oxovanadium(IV) are insulin-mimetic agents currently being investigated in phase II clinical trials for type II diabetes." (PMID 23409868, 2013). "AT supplementation produces a momentous improvement in insulin mediated glucose utilization in healthy people, type-2 diabetics and essential hypertensives." (PMID 24298385, 2013). "The 48-week, randomized, open-label STEP-WiseTM study, conducted in individuals with inadequately controlled Type 2 diabetes on basal insulin and oral anti-diabetic drugs, used two different methods to determine the meal to be targeted for prandial injection." (PMID 22998363, 2013). "Two further classic type 2 diabetes risk alleles, KCNJ11 rs5219 (G) (influencing insulin secretion) and PPARγ rs1801282 (C) (influencing insulin sensitivity) are considered to be very rare and very frequent, respectively, in individuals of African descent." (PMID 24059590, 2013).
type 2 diabetes (continued). "More recently, it has also been demonstrated that reduced insulin clearance predicts the development of type 2 diabetes independently of confounding factors." (PMID 24194886, 2013). "An estimated 2–4% of deaths of people with type 1 diabetes have been attributed to hypoglycemia, and hypoglycemia also occurs in type 2 diabetes with prevalence rates of 70–80% in clinical trials of insulin." (PMID 23543638, 2013). "Tolbutamide is a first generation potassium channel blocker, sulfonylurea oral hypoglycaemic drug to treat Type II diabetes by stimulating the secretion of insulin by the pancreas." (PMID 23977329, 2013). "A decrease in beta cell mass of ≤60% has been reported in type 2 diabetes, which parallels the extent of reduction in glucose-stimulated insulin secretion (GSIS) but, however, considerably lower decrements have been found." (PMID 23542897, 2013). "In regard to β cell function, the incretin effect, i.e., the increased insulin response to glucose, is markedly reduced in patients with type 2 diabetes." (PMID 23717642, 2013). "Measurement of insulin secretion using C-peptide can be helpful in clinical practice: differences in insulin secretion are fundamental to the different treatment requirements of Type 1 and Type 2 diabetes." (PMID 23413806, 2013). "Initial insulin therapy for type 2 diabetes patients is unusual unless the patient is markedly hyperglycemic and/or symptomatic." (PMID 23841986, 2013). "Generally, early intensive insulin therapy controls hyperglycemia and delays β-cell damage and restores β-cell function in type 2 diabetic patients." (PMID 23874448, 2013). "To investigate the source of these differences, we compared insulin sensitivity, insulin secretion, glucose and lipid metabolism in South Asian and Nordic subjects with type 2 diabetes." (PMID 24391858, 2013). "High fat and sucrose diet and low-dose STZ have been known to induce a mild impairment of insulin secretion which is similar to the feature of type 2 diabetes." (PMID 24250711, 2013). "It was shown that resistance to insulin-stimulated glucose uptake, especially in adipose tissue, liver, and muscle brings about type 2 diabetes, one of the most common chronic diseases." (PMID 24348155, 2013). "This study was designed to evaluate the effect of insulin analog initiation therapy on n6 and n3 PUFAs in type 2 diabetic patients during early phase." (PMID 24195588, 2013). "Decreased expression of IRSs or derangement in their signal transduction pathway leads to impaired insulin secretion similar to that seen in type 2 diabetes." (PMID 24371439, 2013). "The treatment of Type 2 diabetes with exogenous insulin significantly improves prognosis for patients, by restoring glycaemic control and consequently reducing morbidity." (PMID 23199058, 2013). "Analogues of this peptide recently emerged as novel pharmacotherapies for treatment of type II diabetes since they reduce gastric emptying, glucagon secretion as well as enhance glucose-dependent insulin secretion." (PMID 24204788, 2013). "Insulin therapy has been extensively used for the management of advance type-2 diabetes in humans, when the endocrine pancreas is exceedingly deficient and patients are overtly hyperglycemic." (PMID 23408938, 2013). "GIP analogues have been developed as potential treatments for type 2 diabetes, and ameliorate impaired insulin release from the pancreas and facilitate the normalisation of insulin signaling and hyperglycaemia." (PMID 23601582, 2013). "It is known that decreased insulin sensitivity plays an important role in the pathogenesis of type 2 diabetes." (PMID 23991018, 2013). "In a preliminary clinical trial, treatment of type 2 diabetic patients with bark extracts of Ficus racemosa resulted in significantly reduced blood glucose levels and increased serum insulin levels." (PMID 23800215, 2013).
type 2 diabetes (continued). "Type II diabetes is a heterogeneous syndrome resulting from progressive impairment of β-cell insulin secretion and insulin resistance in target tissues." (PMID 21977023, 2012). "This study of 4,427 patients measured thigh and calf circumference and insulin resistance and demonstrated that insulin resistance was significantly correlated with thigh and calf circumference in patients with type 2 diabetes." (PMID 22682537, 2012). "Out of the 5 studies using GBR as test diet, 2 studies reported its effects on glycemic and insulin indices over 1-2 h, providing little information on its long-term effects on metabolic control in type 2 diabetes." (PMID 23304216, 2012). "In contrast to humans with diabetes type 2 due to insufficient insulin secretion, the beta cells of ob/ob mice have normal glucose-stimulated insulin secretion and produce large amounts of insulin." (PMID 23186339, 2012). "Many interacted pathways play a role in T2D genetic risks, which includes insulin signalling pathway, type II diabetes pathway, maturity onset diabetes of the young, adipocytokine signalling pathway, and pathways in cancer." (PMID 23281828, 2012). "Our analysis suggests that insulin has beneficial effects on lipids and glucose in patients with type 2 diabetes." (PMID 22081557, 2012). "Type 2 diabetes results from the combination of insulin resistance and defective glucose stimulation of insulin secretion by the endocrine pancreas." (PMID 23056475, 2012). "The Malaysian clinical practice guideline (CPG) for type 2 diabetes was last updated in 2009 and insulin therapy was stated as part of the treatment algorithm." (PMID 22469132, 2012). "Insulin sensitivity and resistance appears to be influential in the development of glucose tolerance and ultimately type II diabetes." (PMID 22970372, 2012). "In humans, circulating RBP4 levels were found to be highly negatively correlated with levels of insulin sensitivity, and to be increased with obesity and in those with type 2 diabetes." (PMID 22587616, 2012). "PPARγ agonists have been proven to be potent insulin sensitizing agents for treating type II diabetes, but induce body weight gain in patients." (PMID 23049539, 2012). "Ferland and colleagues have reported aspartame to induce similar increases in blood glucose and insulin levels to that of sucrose after a meal in type 2 diabetics." (PMID 22853297, 2012). "Glucokinase serves as an insulin sensor in the pancreatic beta cells and is being evaluated as a potential drug target for type 2 diabetes." (PMID 22584726, 2012). "Conversely, enhancement of ER capacity augments leptin-stimulated LepRB activation, and increases insulin sensitivity and type 2 diabetes in obese mice." (PMID 22815920, 2012). "SPPARMs are PPARγ modulators that exhibit potent insulin sensitization activity but are antiadipogenic in animal models of type II diabetes." (PMID 23213321, 2012). "Improvement of glucose homeostasis and delayed onset of type 2 diabetes was followed by monitoring of glucose and insulin levels during the course of the study." (PMID 23236485, 2012). "Type 2 diabetes (T2D) is a disorder characterised by impaired insulin secretion from beta cells and insulin resistance (IR) in peripheral target tissues." (PMID 22506116, 2012). "Whereas studies in obese individuals with type 2 diabetes have shown that following bariatric surgery first-phase insulin can be restored, the improvement observed in our study was independent of any changes in body weight or lifestyle." (PMID 22815837, 2012). "These numbers must be combined with reduced insulin sensitivity and/or blood plasma insulin levels to yield a diagnosis of type 2 diabetes." (PMID 23094144, 2012). "The current data demonstrate that early type 2 diabetes is associated with an increase in the SERCA/PLB ratio and that insulin directly stimulates SERCA expression and relaxation velocity." (PMID 22621761, 2012).